EGF (epidermal growth factor)
Diseases named in the same sentence as EGF in open-access papers (continued):
Sharing a sentence is not in itself a finding about the gene and the disease.
cancer (continued). "The tumor-derived colony-stimulating factor-1 (CSF-1)/EGF paracrine loop helps in the recruitment of TAMs around the blood vessels, which promotes cancer cell escape through various mechanisms." (PMID 32992449, 2020). "ADAM proteins can cleave various substrates, including TNF-α, an epidermal growth factor involved in inflammation and cancer." (PMID 32028607, 2020). "Berberine and Costunolide target different steps of EGFR internalization and degradation, and mutually enhance the inhibition on EGF signaling, resulting in a synergistic anti-cancer effect." (PMID 32298294, 2020). "Epidermal growth factor (EGF): EGF-receptor (EGFR)-mediated signalling is a potent driver of the cell cycle, enhancing proliferation and is implicated in numerous cancer settings." (PMID 33256730, 2020). "Corroborating our findings others showed that in cancer cells EGF influences Ca2+ in a TRPM7-independent manner probably through other TRP channels." (PMID 32706027, 2020). "We discovered CAF secretion of EGF is increased in response to cetuximab and the presence of exogenous EGF results in cancer cell resistance to cetuximab treatment." (PMID 32481658, 2020). "Among platelet-derived growth factors/cytokines, VEGF, EGF and Ang-1 play a crucial role in cancer angiogenesis." (PMID 31991775, 2020). "Cancer cells upregulate proangiogenic factors like angiopoietins (Ang), epidermal growth factor (EGF), fibroblast growth factor (FGF), interleukin 8 (IL-8) etc., to activate compensatory pathways to stimulate blood vessel formation." (PMID 31936832, 2020). "To conclude, our results defined KIAA1199 as an oncogenic protein that promotes cancer cell proliferation and migration by regulating EGF‐mediated signaling pathways." (PMID 32519472, 2020). "HER-2/neu is a member of the human epidermal growth factor (HER) family of transmembrane tyrosine kinases, which is significantly associated with the pathogenesis of various cancer types." (PMID 32458657, 2020). "PDPK1 is a classic effector of the epidermal growth factor (EGF) signaling pathway that can prevent apoptosis and mediate drug resistance in cancer." (PMID 32799866, 2020). "Among the various growth factors and cytokines that are produced by CAFs, TGF-β (Transforming growth factor beta), EGF (Epidermal growth factor), and chemokines were found to play a major role in inducing proliferation and invasion of cancer cells." (PMID 32731484, 2020). "We also verified the role of IRBIT in cancer cell migration by stimulation with oncogenic epidermal growth factor (EGF)." (PMID 32867284, 2020). "The results of this study showed that EGF induced EMT in Caco-2 cancer cells and enhanced cell migrating ability." (PMID 32148496, 2020). "To study in vitro the immunosuppressive properties of MICs, we exploited a well-known method adopted to enrich for CSC population through the generation of cancer spheroids grown in selective medium, containing EGF and bFGF." (PMID 33123122, 2020). "We studied the interactions of MET and EGFR upon stimulation by HGF or EGF in the two cancer cell lines, HeLa and BT-20, which exhibit inverse MET:EGFR expression ratios." (PMID 32316583, 2020). "For instance, reports show TAM-produced ligands such as EGF signal to EGFR on cancer cells to promote cell migration." (PMID 32665556, 2020). "Our results show that the EGF-mediated autocrine loop in cancer cells is a potential player in the interactions between stellate and cancer cells." (PMID 32696951, 2020). "Among molecules affecting cancer cell proliferation, TAMs express epidermal growth factor (EGF), members of the TGFβ and fibroblast growth factors (FGF)." (PMID 32708142, 2020). "TAMs enhance the tumorigenic potential of cancer cells and induce anti-cancer drug resistance through cathepsin β and milk-fat globule epidermal growth factor (EGF)-VIII." (PMID 32595638, 2020).
cancer (continued). "EGF‐mediated downregulation of FOXO4 rewires cancer metabolic programming via enhancing the expression of serine‐glycine‐one‐carbon genes." (PMID 33101846, 2020). "For example, lamellipodial protrusion and directional migration of carcinoma cells towards chemoattractants, such as epidermal growth factor (EGF), depend upon the spatial and temporal regulation of the actin cytoskeleton." (PMID 32844214, 2020). "Saponins from gypsophila plant species have been shown to augment an epidermal growth factor (EGF) targeted toxin for human carcinoma cells and saporin immunotoxins directed against a variety of target molecules for carcinoma and haematological cell lines." (PMID 33228031, 2020). "β-catenin activation via EGF/EGFR induction has been demonstrated in a number of studies using cancer cells." (PMID 30287279, 2019). "Several studies show involvement of aberrant EGF signaling in the development of several cancer types." (PMID 31212861, 2019). "Growth factors, such as EGF, activate multiple downstream signalling pathways and have an important role in cancer progression, including proliferation, invasion and migration." (PMID 31345230, 2019). "While it is possible to study the effect of PD-1 expression on the dynamics of the cancer-immune interaction, it is more interesting to investigate the combined effects of PD-1 (Ksupp) and EGF (eg0) on this process." (PMID 31157216, 2019). "The expression of AQP3 is stimulated by hormones that are commonly increased in cancer, such as EGF and estrogens, but how overexpressed AQP3 accelerates cancer progression is not clear." (PMID 30893772, 2019). "It has been reported that the activation of EGFR by EGF in some cancer cell lines results in NF-κB activation." (PMID 31470515, 2019). "Cancer-associated fibroblasts (CAFs) recruit ITGA5high ATCs to form MUs, which further sustain ATC ITGA5 expression by EGF secretion." (PMID 30710055, 2019). "We also found that the hub genes (e.g., MAPK8, EGF, FALGDS, CCND1, MYC) in this network have been linked to cancer in wide literature reports." (PMID 31080457, 2019). "Overall, these findings suggest that EGF-induced EGFR internalization and nuclear translocation in DUOX1-deficient cancer cells is associated with altered dynamics of EGFR oxidation." (PMID 30890751, 2019). "With this work, we show for the first time, that depletion of ANXA2 in cancer cells leads to enhanced activation of AKT in response to either EGF/EGFR activation or oncogenic H-RasV12 transformation." (PMID 30959964, 2019). "The dual starvation for glutamine and EGF, resulting in the deficiency of ATP and the weakness of EGFR functions, accelerates and reinforces the autophagic protein degradation in cancer cells exposed to the compound VM26." (PMID 31374910, 2019). "NRP2 also regulates the number of EGFR on the surface of cancer cells, thereby controlling EGF-mediated signaling and response to EGFR-targeted therapy." (PMID 30717262, 2019). "As expected, short hairpin RNA-mediated knockdown of GRB7 expression reduces gap closure migration of cancers in response to the EGF treatment." (PMID 31083325, 2019). "In the present study, we identified a novel link between MICAL‐L2 and EGFR, providing a basis for further exploring the role of EGF/EGFR signalling in MICAL‐L2‐facilitated cancer cell migration." (PMID 31034158, 2019). "AuNPs are functionalized also with Doxorubicin (DOX), bonded through the hydrazone-thiol group, and an epidermal growth factor (EGF) peptide to act as an active targeting moiety to cancer cells overexpressing the EGF receptor." (PMID 31475143, 2019). "The fusion of epidermal growth factor (EGF), whose receptor is overexpressed in several cancers has been studied." (PMID 31261673, 2019). "Currently, Escherichia coli-derived recombinant proteins of truncated ErbB kinases, which lack the extracellular domains for their interaction with EGF/neuregulins, are commercially available and often utilized for cancer drug screening." (PMID 31371697, 2019).
cancer (continued). "EGF is involved in cancer progression and both inhibitors and antibodies targeting ErbBs have been developed to treat various cancer types." (PMID 31878047, 2019). "The MAPKs and mTOR signaling pathways have been reported to play crucial roles in EGF-mediated cancer development." (PMID 31167465, 2019). "The inhibitory effects of KP were still seen in the treatment with the presence of EGF, where KP at 15 μg/mL significantly reduced the HeLa cancer cell number at 48, 72, and 96 h." (PMID 31470515, 2019). "The epidermal growth factor (EGF) secreted by TAMs promotes the proliferation and invasion of cancer cells, while VEGF regulates angiogenesis." (PMID 31878087, 2019). "Recent developments dealt with novel combinations of conventional anti-cancer drugs together with biologicals or small compounds specifically targeting certain cancer cell pathways (TKs, EGF, ras/raf, PI3K-Akt, etc.)." (PMID 31561620, 2019). "Collectively, these results confirmed that MTHFD2 was upregulated upon EGF stimulation in some normal and cancer cells." (PMID 30532069, 2019). "The results show that AQP3 is required for EGF-induced cell signaling and cancer progression by a mechanism involving EGF-induced generation of extracellular H2O2, and its intracellular transport by AQP3." (PMID 30893772, 2019). "The modified vaults bound specifically to cancer cells either directly (EGF modified vaults) or as mediated by a monoclonal antibody (anti-EGFR) bound to recombinant vaults containing the Z domain." (PMID 31261673, 2019). "Others, such as FN1, EP300, CASP8, EGF and MAP2K1, which were associated with the pathways involved in cancer, were also hub-node genes." (PMID 31501464, 2019). "Further, we observed selective hindering of EGF-promoted cancer metastasis through synergistic treatment with iEFs and MK2206, a potent pan-Akt inhibitor." (PMID 31428691, 2019). "The contribution of growth factors in cancer is well known; therefore the study of genes incorporated in growth factors signals is also important in study of cancer samples (EGF, TGFB)." (PMID 31164955, 2019). "EGF signaling is involved in cell proliferation and cancer progression, and EGF inhibitors are widely used in cancer therapy." (PMID 31717697, 2019). "Epidermal growth factor (EGF) stimulates cell growth and abnormal EGF signaling is known to promote malignant transformation, cancer progression, and metastasis." (PMID 31167465, 2019). "EGF functions as a ligand to activate the EGF receptor (EGFR) and dysregulation of EGF and/or EGFR is known to cause various types of human cancers." (PMID 31167465, 2019). "Transcription factors important in cancer and proinflammation pathways such as NFkB, Elk-1, C/EBPβ, or AP-1 are activated by both IL-1 ligands and EGF." (PMID 31320902, 2019). "The first was DMEM-F12 medium supplemented with EGF and bFGF, adapted from previous studies, and further referred as cancer stem cell medium (CSC-medium)." (PMID 31181618, 2019). "This autocrine signaling triggers cancer cells to produce CSF-1, which promote epidermal growth factor (EGF) production by macrophages." (PMID 31684193, 2019). "The EGFR and its ligands are overexpressed in many human cancers, and dysregulation of the EGF/R network at multiple levels signals a poor prognosis." (PMID 31805097, 2019). "Previous studies have shown that cancer-associated fibroblasts (CAF) secrete a variety of cytokines in and high levels of growth factors such as EGF, TGF-β, HGF, and FGF-2 into CAF-conditioned media." (PMID 31491033, 2019). "The angiogenesis is likely induced by angiogenetic signals such as VEGF (vascular endothelial growth factor) and EGF (epidermal growth factor), which are secreted by transplanted cancer cells." (PMID 31083409, 2019). "Using VF-FLIM, we quantify and track the evolution of a 10–15 mV Vmem hyperpolarization over minutes following epidermal growth factor (EGF) stimulation of human carcinoma cells." (PMID 31545164, 2019).
cancer (continued). "Together, EGF-stimulated S37 phosphorylation of PKM2 facilitates metabolic reprogramming in cancer cells." (PMID 29468140, 2018). "Accordingly, these data suggest that the AMPK-Skp2-Akt axis regulates EGF-induced glucose metabolism and cancer cell migration." (PMID 30413706, 2018). "Induction of EMT by various growth factors, such as hepatocyte growth factor, transforming growth factor, and EGF, has been clarified in many cancer cell models." (PMID 29681982, 2018). "The Epidermal Growth Factor (EGF) and its receptor, the Epidermal Growth Factor Receptor (EGFR), are involved in cancer patients with poor prognosis, of which 80–90% are associated with HNSCCs." (PMID 30308958, 2018). "Hu-rhEGF-rP64k vaccine is a therapeutic modality that exerts its anti-cancer activity by targeting the immune system, specifically the self-molecule Epidermal Growth Factor (EGF)." (PMID 29661145, 2018). "We detected four tear film proteins involved in several angiogenesis-related pathways, i.e., the PDGF signaling pathway, the EGF signaling pathway, and the CCKR signaling pathway (also linked with cancer) in wet AMD samples." (PMID 29696386, 2018). "In turn CAF-derived TGFα induces epidermal growth factor (EGFR) signaling in cancer cells which stimulates cancer cell growth." (PMID 29854318, 2018). "In these processes, TAMs secrete epidermal growth factor (EGF), and activate its receptor in cancer cells, which enhances invasion capability and motility through increasing invadopodium formation and matrix degradation." (PMID 30483271, 2018). "Here in we demonstrated potential evidence of angiogenic pathway involvement in the cancer biology of HER2+ patients under metronomic anti-EGF therapy." (PMID 29946467, 2018). "Epidermal Growth Factor (EGF) is a well-known growth factor that is overexpressed in many types of cancer." (PMID 29805774, 2018). "Together, our findings indicate a complex mechanism underlying PGE2-induced EGF/EGFR signaling and transcriptional control, which plays a key role in cancer progression." (PMID 29599917, 2018). "Hu-rhEGF-rP64k/Mont cancer vaccine can induces a neutralizing antibody-mediated immune response, against the normal circulating self-protein antigen Epidermal Growth Factor (EGF), which is the main ligand of the Epidermal Growth Factor Receptor (EGF-R)." (PMID 29661145, 2018). "A highly connected interacting network for HABP1 and protein kinase C, a key regulator of cell polarity has been constructed showing Pkcξ is regulated by HABP1 and modulated in EGF-induced cancer cell chemotaxis." (PMID 29535843, 2018). "Translocation of cancer cells can be initiated by chemokines released from host tissues, and growth factors such as EGF secreted by stromal cells." (PMID 29922644, 2018). "Cancer cells stimulated with EGF triggers extracellular signal-regulated kinase 2 (ERK2), serine/threonine protein kinase, to phosphorylate PKM2 at the serine (S) 37 residue." (PMID 29468140, 2018). "Epidermal growth factor (EGF) is known to specifically bind the HER2 receptor of cancer cells, so stimulating them to proliferate and to form metastasis." (PMID 29674690, 2018). "Recently, the studies showed that EGF contributed to the initiation of EMT via activating Myc in many cancers." (PMID 29977916, 2018). "Of note, expression of EGF in cancer cells remained unchanged upon exposure to paracrine SPINK1, precluding the possibility of EGFR activation via an autocrine modality by PCa cells." (PMID 30333494, 2018). "Several lines of evidence have demonstrated that CTEN is upregulated in many types of cancer and participates in cell motility, apoptosis, epidermal growth factor signaling, and tumorigenicity." (PMID 30332774, 2018). "Intensive studies indicate that PKCζ is a key mediator of EGF-induced chemotaxis and is required for cancer cell metastasis." (PMID 29491746, 2018).
cancer (continued). "TGF‐β and EGF can synergistically promote malignant phenotypes, such as epithelial‐to‐mesenchymal transition, which is a crucial process in cancer invasion and metastasis." (PMID 29215776, 2018). "Although TGF‐β alone can promote the invasiveness of cancer, the addition of EGF can enhance this effect." (PMID 29215776, 2018). "CXCL8 (encoding IL-8) activates EGF and MAPK signaling cascades resulting in cancer progression and metastasis in diverse cancer types." (PMID 28038442, 2017). "This was observed in experiments measuring either the cancer cell proliferative ability or their clonogenic propensity in response to EGF." (PMID 29137335, 2017). "The work we have presented here represents a broad foundation upon which a deeper understanding of the mechanisms through which EGF signaling affects cancer can be built." (PMID 28178204, 2017). "The crosstalk between TAMs and cancer cells is required for invasion and metastasis, whereby cancer cells provide CSF1 for TAMs, and in turn TAMs produce EGF that feeds back on cancer cells to stimulate their movement." (PMID 29220404, 2017). "We previously reported that 111In-EGF-Au NP delivered a significant amount of radioactivity to EGFR-positive cancer cells in vitro, leading to radiotoxicity." (PMID 29071190, 2017). "CIMAvax-EGF is a therapeutic cancer vaccine developed to generate specific humoral response against the EGF." (PMID 28261208, 2017). "The first advantage of this dimeric system is the higher avidity of the transporter towards the cancer cell, because each subunit of the heptameric pore is fused to EGF or ZHER2 and therefore has seven possible binding sites on the cell surface." (PMID 28128281, 2017). "Mesenchyme-derived growth factors known to promote cancer cell proliferation (EGF, FGF1, FGF2, and IGF-1) were expressed in different CAF populations to different levels." (PMID 28649646, 2017). "Epidermal growth factor (EGF) and estrogen both contribute to cancer development and have been suggested as upstream regulators of AQP3 expression." (PMID 28991174, 2017). "Many epithelial tumors are known to overexpress EGF and the EGF receptor is a known cancer therapy target." (PMID 28621731, 2017). "Our previous studies explored that miR-152 inhibited the Warburg effect by directly targeting PKM214; while β-catenin had been reported to be an interacting protein of PKM2 in various cancer cells dependent on EGF stimulation." (PMID 29162853, 2017). "This pathway regulates cell proliferation and cancer cell transformation downstream of EGF stimulation, and proteins in this pathway are constitutively active in several human malignancies." (PMID 29221196, 2017). "In summary, we have developed radiolabelled PEGylated EGF-tagged Au NP for targeting EGFR-positive cancer." (PMID 29071190, 2017). "Here, a novel method in NTP-mediated cancer therapeutics was described with enhanced target specificity by treating EGF (epidermal growth factor)-conjugated GNP (gold nanoparticle)." (PMID 28887524, 2017). "Since EGF and its receptor (EGFR) have been reported as an important signaling pathway leading to cancer, EGF was used to promote JB6 transformation." (PMID 28335476, 2017). "This review provides a foundation for utilizing the Drosophila model system for research into EGF effects on cancer." (PMID 28178204, 2017). "The dietary antioxidant cyanidin found in fruits and vegetables appeared to inhibit the NTS- and EGF-induced cancer cell metabolism." (PMID 28316623, 2017). "The sensitivity of cancer cells to growth factors: EGF and IGF-1 alone and in combination, was evaluated following tunicamycin treatment and the role of glycosylation on sensitivity to DXR was determined." (PMID 28223691, 2017). "Epidermal growth factor (EGF) signaling promotes cell proliferation and survival in several types of cancer." (PMID 27935858, 2017).